NPAS1 (neuronal PAS domain protein 1)
Description:
May control regulatory pathways relevant to schizophrenia and to psychotic illness. May play a role in late central nervous system development by modulating EPO expression in response to cellular oxygen level (By similarity). Forms a heterodimer that binds core DNA sequence 5'-TACGTG-3' within the hypoxia response element (HRE) leading to transcriptional repression on its target gene TH (By similarity).
Synonyms: bHLHe11; MOP5; PASD5
Tractability: No criterion of Open Targets' tractability assessment is met for any kind of drug.
Gene: Protein-coding gene on chromosome 19 (47,019,474 to 47,047,242, forward strand). Ensembl gene ENSG00000130751.
Subcellular location: Nucleus
Subcellular location (Human Protein Atlas): Nucleoplasm
Gene Ontology:
Molecular function: DNA-binding transcription factor activity; DNA-binding transcription factor activity, RNA polymerase II-specific; protein heterodimerization activity; RNA polymerase II transcription regulatory region sequence-specific DNA binding; protein dimerization activity
Biological process: central nervous system development; negative regulation of DNA-templated transcription; regulation of transcription by RNA polymerase II; regulation of DNA-templated transcription
Cellular component: chromatin; nucleus
Genetic constraint (gnomAD): Loss-of-function variants: 25 observed, 38.03 expected, observed/expected ratio (o/e) 0.66, 90% interval 0.48 to 0.92. The synonymous counts are far from expectation, so gnomAD's model fits this gene poorly and the ratio says little. Missense variants: 800 observed, 698.65 expected, observed/expected ratio (o/e) 1.15, 90% interval 1.08 to 1.21. Synonymous variants: 393 observed, 314.07 expected, observed/expected ratio (o/e) 1.25, 90% interval 1.15 to 1.36.
Homologues: Orthologues: chimpanzee NPAS1 (99% identical), macaque NPAS1 (99% identical), dog NPAS1 (91% identical), pig NPAS1 (90% identical), mouse Npas1 (87% identical), rat Npas1 (87% identical), guinea pig NPAS1 (73% identical), rabbit NPAS1 (59% identical), zebrafish npas1 (51% identical), Drosophila melanogaster trh (38% identical), Caenorhabditis elegans hif-1 (18% identical). Paralogues in human: NPAS3 (50% identical), SIM1 (30% identical), SIM2 (30% identical), HIF1A (25% identical), HIF3A (24% identical), EPAS1 (24% identical), NPAS4 (17% identical).
Diseases named in the same sentence as NPAS1 in open-access papers:
NPAS1 is named in the same sentence as 8 diseases in open-access papers, as found by Europe PMC text mining. Sharing a sentence is not in itself a finding about the gene and the disease. The quoted sentences say what the papers report.
schizophrenia (4 papers, 2016 to 2020). A major psychotic disorder characterized by abnormalities in the perception or expression of reality. "The neuronal PAS domain proteins NPAS1 and NPAS3 are members of the basic helix-loop-helix-PER-ARNT-SIM (bHLH-PAS) family, and their genetic deficiencies are linked to a variety of human psychiatric disorders including schizophrenia, autism spectrum disorders and bipolar disease." (PMID 27782878, 2016). "NPAS1 (MOP5) was detected only in certain regions of the brain and was connected with neurogenesis and schizophrenia." (PMID 31554340, 2019).
synovial sarcoma (1 paper, 2019). "For group 2 (MPNST and SS) genes related to neural differentiation such as NEURL1 and NPAS1 were identified, which were found to be upregulated in synovial sarcomas, while SCD, an enzyme involved in fatty acid biosynthesis, is more highly expressed in MPNST." (PMID 30785874, 2019).
neurodevelopmental disorder (2 papers, 2019 to 2023). A behavioral and cognitive disorder with onset during the developmental period that involves impaired or aberrant development of intellectual, motor, or social functions. "TFs associated with neurodevelopmental disorders, such as Npas1 and Npas3, are preferentially expressed in DR-6, and Aff2 is enriched within DR-3." (PMID 31647409, 2019).
NPAS1 also shares sentences with these, for which no sentence is quoted: psychiatric disorder (2 papers); autism spectrum disorder (1); bipolar disorder (1); COVID-19 (1); respiratory disorders (1).